MTOR (mechanistic target of rapamycin kinase)
Diseases named in the same sentence as MTOR in open-access papers (continued):
Sharing a sentence is not in itself a finding about the gene and the disease.
endometrial cancer (continued). "Taken together these data suggest that taxane resistance in endometrial cancer cells involves upregulated PI3K/AKT/mTOR pathway activity, however this increase does not reduce – but rather potentially increases – sensitivity to sapanisertib plus serabelisib." (PMID 40360883, 2025). "While approximately 80% of endometrial cancers carry a PI3K/AKT/mTOR pathway mutation, surprisingly there are no approved PI3K/AKT/mTOR pathway targeted agents for this disease." (PMID 40360883, 2025). "After adjusting for potential confounders, body composition types were associated with tumor expression of several proteins that are commonly found in key endometrial cancer signaling pathways, including the PI3K/AKT/MTOR, DNA damage response, and mismatch repair pathways." (PMID 39766121, 2024). "Conversely, stimulating mTOR with MHY1485 reduced GLUT1 levels, These intricate interplays underscore a reciprocal relationship between glycolysis and mTORC1 in ALDH-active endometrial cancer progression." (PMID 39394200, 2024). "Targeting this interaction could potentially enhance endometrial cancer treatment outcomes, even when mTORC1 activation is influenced by PI3K–Akt–mTOR genomic aberrations." (PMID 39394200, 2024). "Reassuringly, the same association between MTA1 and AKT/mTOR/4EBP1 was recently reported in endometrial cancer, in which miR-30c/MTA1 axes regulated cell proliferation, migration, and invasion via AKT/mTOR signaling defining MTA1 as a therapeutic target in endometrial cancer." (PMID 38611022, 2024). "The novelty of our study is the evaluation of WNT-1 and mTOR levels in non-canonical cellular compartments of endometrial cancer of different grades and stages." (PMID 37176048, 2023). "The relationship among UPF1, the mTOR pathway and autophagy has not been reported in endometrial cancer." (PMID 34520393, 2021). "In endometrial cancer, miR-152 inhibited tumor cell growth via targeting novel candidate targets E2F transcription factor 3 (E2F3), tyrosine kinase receptor (MET), and rapamycin-insensitive companion of mTOR (Rictor)." (PMID 34680020, 2021). "As SESN2 inhibits the mTOR activity, we checked whether mTORC1 inhibition in cells with depleted levels of SESN2 influences endometrial cancer cell proliferation and ROS production." (PMID 32899752, 2020). "Similarly, studies on FGF21 in patients with type II endometrium and slim patients in older age seem to confirm that FGF acts as an independent factor in endometrial cancer, via FGFR 2 and the PI3K/Akt, mTOR signaling pathways." (PMID 32570721, 2020). "This suggested SESN2 to function as a negative feedback regulator of mTORC1 to inhibit endometrial cancer growth and progression stimulated by hyperactivation of mTOR signaling." (PMID 32899752, 2020). "mTOR belongs to the PhosphoInositide 3-Kinase (PI3K)-related kinase family (PIKK), and miR-99a has a role in the PI3K/ protein kinase B (Akt) signalling pathway in endometrial cancer through a dual inhibitory effect." (PMID 33023154, 2020). "Previous studies have revealed that combined inhibition of mTOR and FGFR signaling could be a promising anticancer approach in endometrial cancer." (PMID 33193890, 2020). "Using inhibitors of AKT and mTOR, we demonstrated that these kinases play crucial roles in endometrial cancer cell survival and without them, sulforaphane can no longer reduce endometrial cancer cell line viability." (PMID 32443471, 2020).
endometrial cancer (continued). "The pathways included extracellular matrix-receptor interaction, leukocyte trans-endothelial migration, endometrial cancer, bacterial invasion of epithelial cells, PI3-AKT signaling, mTor signaling, protein processing in the endoplasmic reticulum, and focal adhesion." (PMID 30777008, 2019). "In addition, high glucose can increase the activity of glucose uptake and glycolysis by regulating AMPK/mTOR/S6 and MAPK pathways, thereby leading to increased invasiveness of endometrial cancer cells." (PMID 31440472, 2019). "Metformin can significantly inhibit the proliferation of endometrial cancer cells, which may be related to the activation of AMPK signaling and the inhibition of the mTOR signaling pathway." (PMID 31440472, 2019). "Another effective compound used in endometrial cancer cells is ABTL0812, a fatty acid-derived molecule which may targets the PI3K/AKT/mTOR axis." (PMID 31850214, 2019). "Further, we examined The Cancer Genome Atlas (TCGA) for endometrial cancer and found genetic alterations in 95% (229/242) of patients in several key components of the PI3K-mTOR pathway, including PI3KCA (57%), PTEN (67%), PIK3R1 (33%) and mTOR (12%)." (PMID 27980219, 2017). "Overall, our results suggest that PFOA regulates endometrial carcinoma cell migration and invasion through activation of ERK/mTOR signaling, which could promote tumorigenesis." (PMID 27589685, 2016). "Due to the great expectation on novel targeting agents in advanced endometrial cancer, new drugs against specific molecular pathways with particular focus on PI3KCA/AKT/mTOR axis are emerging as promising treatments for endometrial cancer with aggressive phenotype." (PMID 26244161, 2015). "However, relations between mTOR kinase expression and EEC biology warrant further evaluation and are particularly important in the context of only moderate responses observed in endometrial cancer patients treated with mTOR pathway inhibitors." (PMID 22920721, 2012). "Also of note, despite the substantial cross-talk between Estrogen Receptor (ER) signalling and the PI3K/AKT/mTOR pathway, ER status did not impact the potency of serabelisib and sapanisertib in breast and endometrial cancer cell lines." (PMID 40360883, 2025). "Nevertheless, there remain no studies of CD47-PI3K/Akt/mTOR signaling and endometrial carcinoma." (PMID 32984001, 2020). "Therefore, the biological characteristics of paclitaxel resistant endometrial cancer cells and their correlation with PI3K/mTOR signaling were studied in this paper, so as to provide a theoretical basis for clinical treatment of paclitaxel resistant endometrial cancer." (PMID 30175145, 2018). "Various mTOR inhibitors, including everolimus (RA001), temsirolimus (CCI779), and ridaforolimus (AP2357), either as a single agent or combined with other chemotherapeutic or hormonal agents have been evaluated in patients with advanced or recurrent endometrial cancer with promising results." (PMID 28595616, 2017). "Moreover, miR-205 was found to negatively regulate PTEN expression and lead to autophagy and activation of the AKT/mTOR pathway in PR cells, and PTEN protein levels significantly decreased with development of progesterone resistance in endometrial cancer cells." (PMID 28427207, 2017). "In a preoperative window study in obese, nondiabetic endometrial cancer patients, we demonstrate that metformin significantly decreased proliferation in the malignant endometrium, with parallel effects on inhibition of the mTOR pathway." (PMID 25417601, 2015).
endometrial cancer (continued). "However, several ongoing clinical trials aim at exploiting targets supported by recent comprehensive molecular profiling of primary endometrial carcinoma lesion, dominated by trials targeting the phosphatidylinositol 3-kinase (PI3K)/AKT/mammalian target of rapamycin (mTOR) or FGFR2." (PMID 23300780, 2012). "Interestingly, when analyzing the role of the Akt/mTOR signaling pathway in the tumorigenesis and stemness of cancer, we found previous studies indicating that high MELK expression can activate the mTORC1 and mTORC2/AKT signaling pathways and promote the development of endometrial cancer (EC)." (PMID 35440604, 2022). "Corroborating these findings, our research establishes that inhibiting LDHA impedes mTOR activation and restricts cancer cell proliferation, particularly in ALDH-active endometrial cancer spheroids, regardless of K-Ras genomic aberrations." (PMID 39394200, 2024). "The most frequently followed genetic alterations in endometrial cancer are aberrations of PTEN, which is a negative PI3K/AKT/mTOR regulator." (PMID 39188680, 2024). "Furthermore, treatment with mTOR inhibitors reduced colony size and proliferation of a PTEN negative endometrial cancer cell line in 3D culture." (PMID 27980219, 2017).
Hyperglycemia (241 papers, 2009 to 2026). An increased concentration of glucose in the blood. "Hyperglycemia-mediated activation of mTOR in the cardiovascular system has also been associated with cardiac and vascular remodeling and dysfunction that lead to DCM due to decreased insulin signaling." (PMID 39239455, 2024). "Among the targeted therapies, the PI3K/AKT/mTOR pathway inhibitors are well known to cause hyperglycemia." (PMID 39199594, 2024). "The use of PI3K/AKT/mTOR pathway inhibitors plus ET is associated with diarrhea, rash, and hyperglycemia, resulting in discontinuations due to AEs in up to 24% of patients." (PMID 39087959, 2024). "There are several reports that treatment with mTOR inhibitors in various cancers is associated with a high incidence of hyperglycaemia and new-onset diabetes." (PMID 38932873, 2024). "Drugs targeting PI3K/Akt/mTOR pathway were reported to cause hyperglycemia and hyperlipidemia, bone marrow suppression (particularly – anemia, thrombocytopenia, and neutropenia), stomatitis, hepatotoxicity, and pneumonitis." (PMID 37686523, 2023). "As mounting evidence suggests the involvement of mTOR in diabetic bone disease, we provide a comprehensive review of its effects on bone diseases associated with hyperglycemia." (PMID 37298150, 2023). "Because of its crucial role in bone metabolism, the dysregulation of mTOR signaling in hyperglycemia is associated with the bone complications of individuals with DM." (PMID 37298150, 2023). "Long-term hyperglycemia can cause autophagy disorder by inhibiting mTOR, resulting in the loss of retinal ganglion cells." (PMID 35574010, 2022). "This review outlines the normal anatomy of the retina and how hyperglycemia can be involved in the neurodegeneration underlying this disease through over activation or inhibition of the mTOR pathway." (PMID 36388931, 2022). "For example, the IGF1/PI3K/Akt/mTOR system is often hyperactive in cancer cells due to chronic hyperglycemia and hyperinsulinemia, as well as the mutations in genes that code for pathway proteins." (PMID 34579079, 2021). "A second problem comprises the clinical adverse effects associated with PI3K/AKT/mTOR inhibition that include hyperglycemia, hyperlipidemia, bone marrow suppression, pneumonitis, stomatitis, and hepatotoxicity." (PMID 33572326, 2021). "Increased nitrative stress, as well as activation of the mechanistic target of rapamycin (mTOR) pathway—a main regulator of cardiac autophagy—were involved in hyperglycemia-induced loss of RIPerC." (PMID 34445586, 2021). "Two major therapies, targeting cancer growth have been associated with hyperglycemia; mTOR inhibitors (Everolimus and Temsirolimus) and tyrosine kinase inhibitors (Nilotinib and Pazopanib)." (PMID 32498358, 2020). "In context with hyperglycemia and hyperlipidemia, the rapamycin pathway is associated with insulin signaling, and mTOR inhibitors are likely to cause insulin resistance and prevent lipid clearance from blood, which results in high lipid and glucose levels." (PMID 32578154, 2020). "On the contrary, the risk of hyperglycemia was lower in the mTOR inhibitor treatment group than the placebo group." (PMID 31586989, 2019). "The current gold standard pharmacological inhibitor of mTOR is rapamycin, an extremely effective inhibitor of mTOR Complex 1, but it can cause many side effects including hyperglycemia, hyperlipidemia, anemia, eye diseases, and some testicle diseases." (PMID 31105084, 2019). "Collectively, diabetes is closely linked with conditions that cause mTOR activation, namely, excessive caloric intake, even when preceding obesity, insulin resistance, and overt hyperglycemia development." (PMID 30510618, 2018). "SNP rs10515074 in PIK3R1, a gene encoding the 85 kD regulatory subunit of phosphatidylinositol 3-kinase enzyme, which is an upstream member that triggers thePI3K/AKT/mTOR signaling pathway, was associated with hyperglycemia and leucopenia." (PMID 28727815, 2017).
Hyperglycemia (continued). "Although a mechanism based toxic effect associated with PI3K/AKT/mTOR inhibitors, hyperglycaemia is often used as a pharmacodynamic biomarker for clinical decision making and dose setting." (PMID 28806782, 2017). "Though mTOR inhibitors are one risk factor for diabetic nephropathy because they cause hyperglycemia, researchers reported their efficacy in treating diabetic nephropathy." (PMID 27338360, 2016). "Metabolic changes as hyperglycemia (26–57 %) or dyslipemia (52–77 %) are associated mainly with mTOR inhibitors." (PMID 26906039, 2016). "We observed very few metabolic adverse events, such as hypertriglyceridemia or hyperglycemia, which are often associated with mTOR inhibitors." (PMID 27589687, 2016). "Toxicities associated with various mTOR inhibitors that are particularly pertinent to diabetics include gastrointestinal effects, hematological, decreased glucose tolerance, hyperglycemia, and hypertriglyceridemia." (PMID 22132311, 2011). "Notably, toxicity associated with PI3K/AKT/mTOR inhibitors, such as diarrhea, rash, and hyperglycemia, resulted in treatment discontinuation in up to 24% of patients." (PMID 41235919, 2026). "Furthermore, hyperglycemia caused by mTOR inhibitors can also result from reduced insulin secretion." (PMID 39410536, 2024). "Animal models have suggested that the compensatory hyperinsulinemia occurring with PI3K inhibitor-associated hyperglycemia may result in partial reactivation of the PI3K/AKT/mTOR pathway and counter the anti-cancer effectiveness of PI3K inhibitors." (PMID 39437820, 2024). "Additionally, mTOR inhibitors are associated with a high incidence of hyperglycemia and new-onset diabetes with 13–50% of patients treated with these inhibitors." (PMID 39410536, 2024). "Treatment of atherosclerosis would supposedly necessitate a long-term mTOR inhibition, that causes hyperglycemia itself and could deteriorate the deranged metabolism of diabetic patients." (PMID 35845058, 2022). "However, long-term hyperglycemia-related conditions cause mTOR inhibition leading to autophagy dysregulation, hence the reason for the neuronal cell death in DR." (PMID 33637094, 2021). "Furthermore, since hyperglycemia is the most common treatment-related adverse event associated with both first and second generation mTOR inhibitors, metformin has the additional advantage of being licensed as a safe and effective hypoglycemia treatment." (PMID 29554968, 2018). "Previous studies have reported that rapamycin, an mTOR inhibitor, may cause hyperglycemia by inhibiting insulin secretion or insulin resistance." (PMID 28781589, 2017). "Management guideline goals for patients with cancer who develop mTOR inhibitor-associated hyperlipidaemia (elevations in total cholesterol, low-density lipoprotein, and triglyceride levels) or hyperglycemia are to decrease short-term morbidity associated with these AEs." (PMID 27287020, 2016). "However, the administration of inhibitors to the PI3K/AKT/mTOR pathway has been associated with metabolically adverse events, including hyperlipidemia and hyperglycemia (49, –, 51)." (PMID 26023239, 2015). "Hyperglycemia associated mTOR activation leads to glomerular changes like hypertrophy, basement membrane thickening and mesangial proliferation, processes that can be ameliorated by rapamycin, a specific inhibitor of mTOR." (PMID 25948777, 2015). "However, inhibitors of the p-Akt/mTOR pathway such as everolimus, although well tolerated, are reported to be associated with fatigue, hyperglycemia, hypertriglyceridemia, hypercholesterolemia, gastrointestinal syndromes, anorexia, rash, mucositis or headache." (PMID 25436776, 2014). "The induction of insulin/IGF-1-like growth signaling pathways that depend on RAS, AKT, mTOR and other oncogenic proteins has been implicated in aging and a number of age-related diseases in humans, including many for which hyperglycemia and/or excess calorie intact are risk factors." (PMID 21076178, 2010).